DUSP4 (dual specificity phosphatase 4)
Diseases named in the same sentence as DUSP4 in open-access papers (continued):
Sharing a sentence is not in itself a finding about the gene and the disease.
skin melanoma (3 papers, 2010 to 2022). "In BRAF WT skin melanoma, patients expressing high levels of DUSP4 mRNA had a better response to selumetinib." (PMID 36576731, 2022). "Although DUSP4 expression has been reported previously in skin melanomas, and as a potential biomarker for patient response to MEK inhibition with its upregulation correlating with a positive response, it has not been described previously in UM." (PMID 33008022, 2020). "DUSP4 and OPN were upregulated in cutaneous melanoma in comparison to normal skin or benign nevi." (PMID 20663135, 2010).
triple-negative breast carcinoma (3 papers, 2016 to 2019). An invasive breast carcinoma which is negative for expression of estrogen receptor (ER), progesterone receptor (PR), and human epidermal growth factor receptor 2 (HER2). "Baglia concluded that low DUSP4 expression is a predictor of recurrence and death in triple-negative breast cancer patients." (PMID 31030473, 2019).
asthma (2 papers, 2023 to 2025). "Consistently, human bronchial biopsy specimens revealed elevated DUSP4 expression in airway epithelial cells from patients with severe asthma compared with those with moderate asthma, further supporting the clinical relevance of this pathway." (PMID 41208877, 2025). "Consequently, our findings suggest that the absence of BMAL1 results in the resistance of airway epithelial cells to GC due to the inhibition of GR phosphorylation via the DUSP4-p38MAPK axis in HDM-induced asthma." (PMID 41208877, 2025). "Importantly, DUSP4 inhibition restored p38MAPK activity and GR function, highlighting the DUSP4-p38MAPK-GR axis as a potential therapeutic target for circadian-related GC resistance in asthma." (PMID 41208877, 2025). "Furthermore, immunofluorescence staining showed higher DUSP4 expression in airway epithelium from patients with severe asthma compared with those with moderate asthma, suggesting DUSP4 may contribute to the pathogenesis and severity of asthma." (PMID 41208877, 2025). "To further validate the therapeutic potential of DUSP4 inhibition in vivo, we administered the DUSP4 inhibitor BCI to Bmal1-/- mice with HDM-induced asthma in combination with DEX treatment." (PMID 41208877, 2025).
atherosclerosis (2 papers, 2022 to 2025). A disease characterized by the build-up of fatty material and calcium deposition in the arterial wall resulting in partial or complete occlusion of the arterial lumen. "In atherosclerotic mouse models, knocking out or silencing the DNMT3A gene in macrophages prevents the methylation of Dusp4, thereby hindering plaque regression in mouse atherosclerosis." (PMID 41000074, 2025). "In the clearance of apoptotic cells in atherosclerosis disease models, the downstream signaling pathways (i.e., PGE2 expression process) activated by the CD36-ERK1/2 signaling pathway are limited by negative feedback regulation mediated by DUSP4." (PMID 41000074, 2025).
autoimmune disease (2 papers, 2019 to 2026). A disorder resulting from loss of function or tissue destruction of an organ or multiple organs, arising from humoral or cellular immune responses of the individual to their own tissue constituents. "DUSP4-deficient mice display decreased T-cell-secreted IL-17A; DUSP4-deficient mice are resistant to autoimmune disease induction in the EAE model." (PMID 31766293, 2019). "Downregulation of DUSP1, DUSP3, DUSP11, and DUSP22, as well as upregulation of DUSP4, DUSP6, and DUSP23 are involved in human autoimmune diseases." (PMID 42087139, 2026). "DUSP2, DUSP4, DUSP7, DUSP10, DUSP12, DUSP22, and DUSP23 are involved in human autoimmune diseases, including SLE." (PMID 31766293, 2019).
autoimmune encephalitis (2 papers, 2015 to 2019). Inflammation of the brain secondary to an immune response triggered by the body itself. "Our in vivo data showed that DUSP4 mice were more resistant to the induction of autoimmune encephalitis, while in vitro differentiations revealed enhanced iTreg and reduced Th17 polarization in DUSP4-deficient T cells." (PMID 26710253, 2015).
cholangiocarcinoma (2 papers, 2023 to 2025). A carcinoma that arises from the intrahepatic biliary tree (intrahepatic cholangiocarcinoma) or from the junction, or adjacent to the junction, of the right and left hepatic ducts (hilar cholangiocarcinoma). "We found a significant increase (p = 0.043, Mann–Whitney test) of DUSP4 protein levels relative to β-actin in the 7 KRAS mutated cholangiocarcinoma cell lines when compared to KRAS wildtype CCA cell lines." (PMID 37946160, 2023). "The study also identified a correlation between RAS pathway activation and DUSP4/6 expression in both HCC and cholangiocarcinoma (CCA), suggesting broader relevance." (PMID 40943262, 2025).
clear cell renal cell carcinoma (2 papers, 2021 to 2022). "Loss of DUSP4 expression in clear cell renal cell carcinoma was significantly correlated with old age (p = 0.033), high histologic grade (p < 0.001), tumor necrosis (p < 0.001), and high pT category (p < 0.001)." (PMID 34679636, 2021). "Therefore, we evaluated the clinicopathological implications of DUSP4 expression in clear cell renal cell carcinoma by performing immunohistochemistry (IHC)." (PMID 34679636, 2021).
colorectal adenocarcinoma (2 papers, 2015 to 2017). The most common type of colorectal carcinoma. "Overall and disease-free survival was associated with DUSP4 expression in colorectal adenocarcinoma." (PMID 29100381, 2017). "We investigated the correlation between DUSP4 expression and clinicopathological parameters to assess the clinicopathological significance of DUSP4 expression in colorectal adenocarcinoma." (PMID 25688264, 2015). "The purpose of our study was to clarify the exact role of DUSP4 expression in colorectal adenocarcinoma." (PMID 25688264, 2015). "The impact of DUSP4 expression on survival in 439 patients with colorectal adenocarcinoma was evaluated." (PMID 25688264, 2015). "DUSP4 protein is frequently upregulated in colorectal adenocarcinoma and may play an important role in carcinogenesis and cancer progression and may be a marker of adverse prognosis." (PMID 25688264, 2015). "In conclusion, we investigated DUSP4 expression in a large series of colorectal adenocarcinoma." (PMID 25688264, 2015). "Our results suggest that DUSP4 may play a role as a cancer promoter, not as a tumor suppressor in colorectal adenocarcinoma." (PMID 25688264, 2015).
depression (2 papers, 2014 to 2022). "For example, cg12721804, which is hypermethylated in affected twins (Δβ = +.06, p = .001), is located in the last exon of DUSP4 (also known as mitogen-activated protein kinase phosphatase 2), which has been shown to be unregulated in the brains of individuals with depression who committed suicide." (PMID 24929637, 2014).
diffuse large B-cell lymphoma (2 papers, 2017 to 2021). "Promoter methylation of the DUSP4 gene associated with loss of DUSP4 expression has been reported in several types of cancer, including diffuse large B-cell lymphoma." (PMID 34679636, 2021).
endometrial cancer (2 papers, 2021 to 2023). Primary or metastatic malignant neoplasm involving the endometrium (mucous membrane that lines the endometrial cavity). "The role of FN1, which encodes fibronectin, and DUSP4, which encodes dual-specificity protein phosphatase 4, in endometrial cancer is not well understood." (PMID 34485158, 2021). "Although DUSP4 expression can be detected in patients with various malignancies, including endometrial cancer, its levels decrease in more advanced stages of the disease, suggesting that the MAPK pathway is activated in patients in advanced cancer stages." (PMID 38071325, 2023). "Low DUSP4 expression was indicative of poor overall survival (OS) and relapse-free survival (RFS) in endometrial cancer patients." (PMID 38071325, 2023). "Additionally, the four genes (FN1, DUSP4, LEF1, and SMAD9) identified can shed light on the mechanisms of recurrence in endometrial cancer." (PMID 34485158, 2021). "The result was confirmed through proteomics database exploration, revealing negative correlations between ARID1A, DUSP4, and MAPK molecules in large published datasets of endometrial carcinomas." (PMID 38071325, 2023).
ischemia (2 papers, 2017 to 2022). A hypoperfusion of the BLOOD through an organ or tissue caused by a PATHOLOGIC CONSTRICTION or obstruction of its BLOOD VESSELS, or an absence of BLOOD CIRCULATION. "The overexpression of DUSP1 has a neuroprotective effect in response to ischemia and, together with DUSP4, they protect motor axons from degradation." (PMID 36227898, 2022). "Previously, we demonstrated that DUSP4−/− hearts sustain a larger infarct and have poor functional recovery, when isolated hearts were subjected to ischemia/reperfusion." (PMID 28484701, 2017).
liver cancer (2 papers, 2017 to 2025). An epithelial or non-epithelial malignant neoplasm that arises from the liver. "In line with the notion that DUSP4 and DUSP6 act as negative feedback regulators, limiting MAPK signalling to prevent oncogene-induced senescence, their silencing increased cell proliferation and ERK1/2 activation in liver cancer cells." (PMID 40943262, 2025).
lymphoma (2 papers, 2014 to 2021). A malignant (clonal) proliferation of B- lymphocytes or T- lymphocytes which involves the lymph nodes, bone marrow and/or extranodal sites. "The promoter methylation of LRP12, CDH1, BMPER and DUSP4 was 100%, 91%, 55%, and 32% across all analyzed lymphoma types included in the validation series, respectively." (PMID 25226156, 2014). "Taken together, we identified several genes (BMPER, BMP7, CDH1, DUSP4 and LRP12) which were frequently methylated in major lymphoma types." (PMID 25226156, 2014). "However, to the best of our knowledge, this is the first time BMPER, BMP7, DUSP4 and LRP12 are reported to be methylated in lymphoma." (PMID 25226156, 2014).
metastatic cancer (2 papers, 2018 to 2025). A carcinoma which has spread from the original site of growth to another anatomic site. "We found DUSP4 to be significantly downregulated, its decreased expression being associated with metastatic cancer." (PMID 40946111, 2025).
myopia (2 papers, 2008 to 2024). "The overall categories in the differentially expressed genes during myopia onset and progression share only three genes in retina: LONRF1, RAD54L2 and DUSP4." (PMID 39028695, 2024).
renal fibrosis (2 papers, 2022 to 2024). A final common manifestation of a wide variety of chronic kidney diseases characterized by glomerulosclerosis and tubulointerstitial fibrosis. "Both Dusp1 and Dusp4 suppress the progression of renal fibrosis by inhibiting JNK activity." (PMID 39267721, 2024). "DUSP4 degradation promoted p38 activation, leading to renal fibrosis and endometrial fibrosis." (PMID 34236463, 2022). "Similarly, Dusp4 inhibits JNK phosphorylation to slow down renal fibrosis, indicating that the JNK signaling pathway promotes renal fibrosis." (PMID 39267721, 2024).
uveal melanoma (2 papers, 2022 to 2025). A melanoma derived from melanocytes of the uveal tract. "Dual-specificity phosphatase 4 (DUSP4) inactivates factors in the mitogen-activated protein kinase (MAPK) signaling cascade, activated in uveal melanoma (UM) by mutations in upstream G-protein α subunits GNAQ/11 in >90% cases." (PMID 36576731, 2022).
alopecia (1 paper, 2022). Hair loss usually from the scalp. "DUSP4 (dual specificity phosphatase 4) and DUSP7 (dual specificity phosphatase 7) were upregulated in giant pandas with alopecia." (PMID 35413801, 2022).
astrocytoma (1 paper, 2017). "Moreover, high expression of 7 of the high-malignant genes (C7ORF46, DUSP4, HS3ST3B1, ODZ1, TTL, VAV3, ZDHHC23) or low expression of 4 of the low-malignant genes (AKR1C3, ARHGEF10L, SMAD7, ST3GAL6) was associated with a lower progression free survival probability of grade III astrocytoma patients." (PMID 29152145, 2017).
B-cell lymphoma (1 paper, 2014). "We focused on major types of B-cell lymphoma (BL, DLBCL ABC, DLBCL GCB, FL and PMBL) and demonstrated that the gene promoters of LRP12 (94%), CDH1 (92%), and BMPER (58%) were methylated at a high frequency, whereas DUSP4 and BMP7 showed lower methylation frequencies (32% and 22%, respectively)." (PMID 25226156, 2014).
bipolar disorder (1 paper, 2007). A disorder of the brain that causes unusual shifts in mood, energy, activity levels and the ability to carry out day-to-day tasks. "For example, 10 genes among the 16 confirmed genes (Cacng2, Dnajc3, Dusp4, Gpc6, Mbp, Nov, Phf21b, Atxn10, Xbp1, and Zfyve28) have their human orthologs located within a 10 Mb region flanking the linkage markers for bipolar disorder, and thus merit further study." (PMID 18028544, 2007).
diabetical nephropathy (1 paper, 2023). "DUSP4 and 6 have both been found to be decreased in diabetical nephropathy models." (PMID 36922538, 2023).
endometriosis (1 paper, 2023). The growth of functional endometrial tissue in anatomic sites outside the uterine body. "To study the effect of ectopic DUSP4 expression, we utilized another cell line, ES2, which was derived from human ovarian clear cell carcinoma, a tumor type related to endometriosis." (PMID 38071325, 2023).
Glucose intolerance (1 paper, 2023). Glucose intolerance (GI) can be defined as dysglycemia that comprises both prediabetes and diabetes. "DUSP4 overexpression did not affect glucose tolerance in control mice but significantly improved glucose intolerance and reduced plasma insulin levels in Dex-treated mice." (PMID 37253782, 2023).
heart failure (1 paper, 2016). Inability of the heart to pump blood at an adequate rate to meet tissue metabolic requirements. "Similarly to our results, increased expression levels of ACE2, NRG1, DUSP4 and LIF have also been found in human heart failure." (PMID 26537877, 2016).
inflammatory bowel disease (1 paper, 2023). A spectrum of small and large bowel inflammatory diseases of unknown etiology. "Among these genes, Dusp4, Epha2, Atp11a, and Tns4 are reported to be overexpressed in human CRC, while the expression of Thbs1 is increased in patients with inflammatory bowel disease." (PMID 37296911, 2023).
ischemic heart disease (1 paper, 2017). "This study demonstrates that DUSP4 is an excellent therapeutic target for ischemic heart disease and vascular dysfunction." (PMID 28484701, 2017). "Overall, DUSP4 may serve as an excellent molecular target for the treatment of ischemic heart disease." (PMID 28484701, 2017).
lymph node metastasis (1 paper, 2015). "We evaluated DUSP4 expression in 23 samples of normal colorectal tissue, 50 samples of tubular adenoma, 439 samples of adenocarcinoma, 56 samples of lymph node metastasis, and 53 samples of distant metastasis." (PMID 25688264, 2015). "Mean DUSP4 expression score was 0.56 in normal colorectal tissue, 0.36 in tubular adenoma, 2.58 in adenocarcinoma, 2.10 in lymph node metastasis, and 4.75 in distant metastasis." (PMID 25688264, 2015). "DUSP4 expression was positive in 2 cases (8.7%) of normal colorectal tissue and 2 cases (4.0%) of tubular adenoma; however, DUSP4 expression was positive in 166 cases (37.8%) of adenocarcinoma, 19 cases (33.9%) of lymph node metastasis, and 32 cases (60.4%) of distant metastasis." (PMID 25688264, 2015). "In addition, DUSP4 was more frequently expressed in cases of distant metastasis compared to that in cases of adenocarcinoma and lymph node metastasis (P < 0.001)." (PMID 25688264, 2015).
malaria (1 paper, 2024). Malaria is a serious and sometimes fatal disease caused by a parasite that commonly infects a certain type of mosquito which feeds on humans. "Mice deficient in DUSP4 were more resistant to infections by both RNA and DNA viruses but more susceptible to malaria parasites." (PMID 38383887, 2024).
multiple sclerosis (1 paper, 2015). A progressive autoimmune disorder affecting the central nervous system resulting in demyelination. "We first subjected WT and DUSP4-/- mice to the induction of EAE, an autoimmune mouse model of human multiple sclerosis, in which the symptoms are ameliorated by Treg but aggravated by Th17 cells." (PMID 26710253, 2015).
non-small cell lung carcinoma (1 paper, 2020). A group of at least three distinct histological types of lung cancer, including non-small cell squamous cell carcinoma, adenocarcinoma, and large cell carcinoma. "The MAP kinase phosphatase DUSP4 has been implicated in CRC proliferation and in promoting E-cadherin expression in non-small cell lung cancer." (PMID 33057364, 2020).
osteoporosis (1 paper, 2025). A condition of reduced bone mass, with decreased cortical thickness and a decrease in the number and size of the trabeculae of cancellous bone (but normal chemical composition), resulting in increased fracture incidence. "MAPKs are widely regarded as important therapeutic targets for inflammatory diseases, including osteoporosis, but the involvement of DUSP4 in osteoclast MAPK regulation has not been previously reported." (PMID 40177487, 2025).
psoriasis (1 paper, 2024). An autoimmune condition characterized by red, well-delineated plaques with silvery scales that are usually on the extensor surfaces and scalp. "We demonstrated a potential relationship between DUSP1 and miR-34a; DUSP4 and miR-34a, miR-382, and miR-3188; MAPK9 and miR-1275, MAP2K7 and mir-200-5p; MAP3K2 and mir-200-5p, which may be the subject of further research in the context of psoriasis." (PMID 38445655, 2024). "Nevertheless, we demonstrated a potential relationship between DUSP1 and miR-34a; DUSP4 and miR-34a, miR-382, and miR-3188; MAPK9 and miR-1275, MAP2K7 and mir-200-5p; MAP3K2 and mir-200-5p, which may be the subject of further research in the context of psoriasis." (PMID 38445655, 2024).
tubular adenoma (1 paper, 2015). A usually polypoid neoplasm arising from the glandular epithelium. "In our study, we found that DUSP4 was more frequently expressed in cases of adenocarcinoma and lymph node metastasis compared to that in cases of normal colorectal tissue and tubular adenoma (P < 0.001)." (PMID 25688264, 2015). "DUSP4 was more frequently expressed in adenocarcinomas and lymph node/distant metastases compared to that in normal colorectal tissues and tubular adenomas (P < 0.001)." (PMID 25688264, 2015). "DUSP4 was more frequently expressed in adenocarcinomas and lymph node/distant metastases compared to that in normal colorectal tissues and tubular adenomas." (PMID 25688264, 2015).